RNU6-506P (RNA, U6 small nuclear 506, pseudogene)
Gene: Small nuclear RNA gene on chromosome 4 (139,231,026 to 139,231,119, reverse strand). Ensembl gene ENSG00000252362.
Homologues: Orthologues: chimpanzee U6 (100% identical), rat LOC120101165 (80% identical), mouse Gm22359 (74% identical). Paralogues in human: RNU6-1060P (90% identical), RNU6-116P (89% identical), RNU6-761P (89% identical), RNU6-842P (89% identical), RNU6-1019P (88% identical), RNU6-15P (88% identical), RNU6-187P (88% identical), RNU6-19P (88% identical), RNU6-25P (88% identical), RNU6-33P (88% identical), RNU6-41P (88% identical), RNU6-698P (88% identical), and 1289 more.